CCND1 (cyclin D1)
Diseases named in the same sentence as CCND1 in open-access papers (continued):
Sharing a sentence is not in itself a finding about the gene and the disease.
breast cancer (continued). "Consistent with its suspected role as an endocrine disruptor, the estrogen-dependent breast cancer signaling pathway was marginally enriched (p-value = 0.043) because three genes (EGFR, ESR1 and CCND1) were used to make the inference." (PMID 23144783, 2012). "In any analysis examining the relevance of cyclin D1 protein in breast cancer, failing to remove the CCND1 amplified cases biases the cyclin D1 overexpressed group by artificially inflating the number of cyclin D1 “high” tumors with a worse clinical outcome." (PMID 22924091, 2012). "Although amplification of HER2, C-MYC, CCND1 and FGFR1 has been reported in breast cancers, their role in the progression of in situ to invasive breast carcinoma is unclear." (PMID 22863309, 2012). "miR-195 was shown to inhibit cyclin D1 in HCC and breast cancer, CCND3 in glioblastoma, CDK4 in bladder cancer, CDK6 in HCC, E2F3 in HCC and glioblastoma, BCL-2 in breast and colorectal cancer, RAF1 in breast cancer, and GLUT3 in bladder cancer." (PMID 23335942, 2012). "This study was conducted after finding the inhibitory effect of auraptene on cyclin D1 protein expression in MCF-7 cells and rat mammary tumors." (PMID 23320178, 2012). "Recently, one report showed that Rab27a affects the invasive and metastatic potential of breast cancer cells by modulating the secretion of IGF-II, which regulates the expression of p16, VEGF, uPA, cathepsin D, cyclin D1, and MMP-9." (PMID 23029308, 2012). "In conclusion, copy number gain of the genes CCND1 (11q13), TRAF4 (17q11), CDC6 (17q21), and MTDH (8q22) is very common in male breast cancer (>40 %) and these genes probably play a role in male breast carcinogenesis." (PMID 22527098, 2012). "Studies indicate that many tumors have overexpression of cyclin D1, such as mantle cell lymphoma (CML), nonsmall cell lung cancer (NSCLC), breast cancer, head and neck cancer, and esophageal cancer." (PMID 22848779, 2012). "Compared to female breast cancers, EGFR (p = 0.005) and CCND1 (p = 0.041) copy number gain was more often seen in male breast cancer, while copy number gain of EMSY (p = 0.004) and CPD (p = 0.001) and amplification in general was less frequent." (PMID 22527098, 2012). "Comparative studies have also shown that chemically-induced mammary carcinomas, as with their human counterparts, have altered TGFB, erbB2, and cyclin D1 expression." (PMID 23508728, 2012). "To further substantiate these findings we aimed to delineate the link between CCND1, ID1 and EMT, as well as clinical properties in primary breast cancer." (PMID 21955753, 2011). "The most significant ones include TFF1, CCND1, IGFBP4, C3, ADORA1, GREB1, and MYC, which have been shown by candidate gene analysis to be estrogen regulated genes in breast cancer cell lines." (PMID 21878096, 2011). "In addition, patients with tumors over-expressing Cyclin D1 have been shown to have a particularly poor prognosis; however, over-expression of Cyclin D1 has been demonstrated for a vast series of human malignancies including breast cancers, esophageal cancers and pancreatic cancers." (PMID 21347341, 2011). "For instance, Myc, CCND1, FOS and EGR3 are well-studied ERα targets promoting breast cancer growth and progression." (PMID 22125492, 2011). "To explore the relationship between MUC1-C expression and β-catenin activity in human breast cancers, we conducted IHC analysis of MUC1-C, β-catenin, c-Myc and Cyclin D1 in human breast cancers and normal tissues." (PMID 21533058, 2011). "In our study, miR-34b has been showed to inhibit cell growth by targeting cyclin D1 and JAG1, both of which are crucial genes covering various types of breast cancer." (PMID 22113133, 2011). "Suppression of kin17 blocked cell cycle progression and decreased the expression of cyclin D1 and ERK1/2 activity in breast cancer cells." (PMID 21980430, 2011).
breast cancer (continued). "The other breast carcinoma cell line tested MDA-MB-453, bearing a large deletion in cyclin's D1 3'UTR, responded with unaltered cyclin D1 mRNA upon PGA2 treatment." (PMID 21835052, 2011). "Transgenic mice constitutively expressing either MMTV-cyclin D1 or MMTV-c-Myc develop mammary hyperplasia and mammary carcinomas." (PMID 21533058, 2011). "So, it was demonstrated that cyclin D1/CDK4 complex interacts with filamin A (member of the actin - binding filamin protein family) and influences the migration and invasion potential of breast cancer cells." (PMID 21176227, 2010). "Furthermore, upregulation of miR-96 in breast cancer cells resulted in modulation of their entry into the G1/S transitional phase, which was caused by downregulation of cyclin-dependent kinase (CDK) inhibitors, p27Kip1 and p21Cip1, and upregulation of the cell-cycle regulator cyclin D1." (PMID 21203424, 2010). "In endoderm formation, β-catenin interacts with Sox17 independently of TCF-4 to activate endoderm genes and in breast cancer, β-catenin and Sox2 interact independently of TCF-4 to activate Cyclin D1." (PMID 20811503, 2010). "In addition, stabilization of β-catenin and amplification of its target gene, cyclin D1, is documented in > 50% of breast carcinomas, suggesting that the downstream effectors of the Wnt cascade could also be activated through abnormalities in other signaling pathways." (PMID 20565980, 2010). "S3I-201 inhibited Stat3 homodimerization, DNA binding, induction of cyclin D1, Bcl-xL and survivin and induced apoptosis of v-Src-transformed NIH3T3 cells and breast cancer cell lines with constitutively active Stat3 in the 30 to 100 μM range." (PMID 19274102, 2009). "Cyclin D1 over-expression has been observed in DCIS, suggesting a possible role in breast cancer development." (PMID 22276018, 2009). "Overall, the results of the current study have demonstrated that citrus auraptene suppressed human breast carcinoma proliferation and IGF-1 induced protein expression of cyclin D1 in vitro." (PMID 19640308, 2009). "By CGH analysis of breast cancer samples, we identified CTTN and FADD as co-amplified with CCND1 at the 11q13 locus, and CHK1 as a marker for the frequently occurring distal 11q deletion." (PMID 18823530, 2008). "The CCND1 and CTTN oncogenes have been putatively proposed as candidate genes for the emergence and maintenance of this amplification event in breast cancer." (PMID 18823530, 2008). "In this report we demonstrate that metformin-sensitive breast cancer cells arrest in G0/G1 due to activation of AMPK, downregulation of cyclin D1, and enhanced binding of CDK2 by p27Kip1 and p21Cip1." (PMID 19046439, 2008). "Incident breast cancer cases from the MDCS were classified according to tumour type, grade, oestrogen receptor (ER) status, expression of p27, cyclin D1 and cyclin E, and proliferation (Ki67)." (PMID 17254341, 2007). "We therefore documented the neoplastic nature of the cells by assessing the gene status of other frequently amplified oncogenes in breast carcinomas, especially CCND1 (cyclinD1) and MYC." (PMID 17262082, 2007). "To more closely examine the responses of some of these cell cycle regulatory molecules to sanguinarine, we used immunocytochemical methods to visualize cyclin D1 and topoisomerase II behavior in MCF-7 breast cancer cells." (PMID 16512916, 2006). "Our findings indicate that a single dose of 5 μM sanguinarine results in a striking relocalization of cyclin D1 and topoisomerase II from the nucleus to the cytoplasm of MCF-7 breast cancer cells, along with an arrest of proliferation for at least six days." (PMID 16512916, 2006).
breast cancer (continued). "In another study with MMTV-cyclin D1 (MP1) transgenic mice, 8 out of 16 mice developed mammary tumors with a mean age of 113 weeks (in an FVB/N versus FVB/SV129 background)." (PMID 16536875, 2006). "Surprisingly, we observed the majority of cyclin D1 is detected in the cytoplasmic fraction of untreated, asynchronous exponentially growing MCF-7 and MDA-MB231 breast cancer cells." (PMID 16503970, 2006). "In addition, anti-cyclin D1 therapy may be highly specific for treating human breast cancer." (PMID 16504004, 2006). "Along the same line, in primary breast cancers, a positive correlation was established between high levels of nuclear EGFR and expression of cyclin D1 and Ki-67, two markers of active proliferation." (PMID 17049074, 2006). "The effect of overexpression of cyclin D1 on the outcome of tamoxifen treatment is controversial: overexpression of cyclin D1 messenger RNA was found to be predictive of poor prognosis in lymph node positive, OR-α-positive breast cancer, which would support the hypothesis raised above." (PMID 11875707, 2002). "One-third of these loci affected breast cancer oncogenes, whose amplifications were validated with specific probes: 17q12 (two cell lines with ERBB2 amplifications), 11q13 (two with cyclin-D1), 8p11–p12 (two with FGFR1) and 10q25 (one with FGFR2)." (PMID 10604729, 1999). "However, in contrast to vascular SMCs, miR-193a exhibits anti-proliferative actions in breast cancers cells and also inhibits CDK4 and Cyclin D1, while these proteins were upregulated in our study." (PMID 40801565, 2025). "Similarly, miR-425-5p overexpression upregulates Cyclin D1 protein levels and activates PI3K/AKT signaling, both of which contribute to breast cancer development (Zhang LF." (PMID 41230330, 2025). "Unlike in breast cancer, where Cyclin D1 influences neoadjuvant chemotherapy choices, pancreatic cancer lacks clinical trial data supporting Cyclin D1‐based treatment decisions." (PMID 40051490, 2025). "Indeed, under the condition of siSNRPE RNA, tumor cells exhibited notably diminished level of Cyclin D1 compared to the siControl RNA group, corroborating the suppressive effect of SNRPE silencing on the cell cycle process of breast cancer cells." (PMID 40386046, 2025). "In breast cancer, NF-κB activation via RANK- or PAK5 (P21cdc42/rac1-activated kinase 5)-mediated phosphorylation of RelA enhances cyclin D1 expression by facilitating NF-κB nuclear translocation and binding to the cyclin D1 promoter, thereby accelerating cell cycle progression." (PMID 40562870, 2025). "(2013) illustrated that Sitosterol treatment led to G1 arrest in human breast cancer MDA-MB-231 cells, corresponding to reduced levels of cyclin D1 and cyclin-dependent kinase (CDK) and increased levels of p21/Cip1 and p27/Kip1 proteins involved in inhibiting the kinase activity of CDK." (PMID 41438988, 2025). "Further, our data suggest that SSD may exert its anti-breast cancer effects via ESR1 and the downstream targets (CCND1 and c-Myc)." (PMID 40708058, 2025). "Further study demonstrated that targeting the Akt/mTOR pathway could control the protein expressions of cyclin D1 and CDK4, thus contribute to the development of drug resistance in breast cancer." (PMID 41460862, 2025). "Previous studies in human breast cancer cell lines (MCF-7, ZR-75-1, T47D, MDA-MB-231, MDA-MB-468, and SK-BR3) have shown that treatment with CBD delivered in DMSO induces G0-G1 arrest through CB1 receptor activation, leading to downregulation of cyclin D1." (PMID 40870993, 2025). "In breast cancer cell lines, a particular anacardic acid congener (AnAc 24:1n5) may suppress the expression of endogenous estrogen regulating genes such CTSD, CCND1, and TFF1." (PMID 39912983, 2025). "It was found that quercetin suppressed breast cancer stem cells (CD44+/CD24−) derived from the MCF7 cell line through the down-regulation of m-TOR, PI3K, and PI3K-AKT pathways and the decreased expression of Bcl-2 protein and cyclin D1." (PMID 39859345, 2025).
breast cancer (continued). "This aligns with existing literature that identifies chromosomes 17 and 11 as regions frequently involved in breast cancer progression, primarily due to the presence of oncogenes like ERBB2 (Her2) and CCND1, which are known drivers of cell proliferation and tumor growth through gene amplification." (PMID 39596229, 2024). "For instance, The ShuTong Capsule plays a role in ERα positive breast cancer cell lines MCF7 and T47D by down-regulating Cyclin D1 and ERα, the downstream target genes of the Wnt/β-catenin signaling pathway, thereby inhibiting breast cancer cell cycle progression." (PMID 38783943, 2024). "In breast cancer cells with FGFR1 amplification (CAMA1 and MDA-MB-134), FGF2 elevated non-canonical FGFR downstream signaling pathways, especially JAK-STAT pathway, to promote p21 expression and modulate the ratio of p21/CCND1 to drive cell cycle arrest." (PMID 38553760, 2024). "Furthermore, we identified additional breast cancer genes deleted more frequently in warm/hot tumors than in cold tumors (BAP1, PBRM1, NOTCH1, CCND1, RB1)." (PMID 38714665, 2024). "In summary, our findings strongly support the hypothesis that DDX in combination with palbociclib can potentially treat ER+ and ER− breast cancers and perhaps prevent palbociclib resistance by targeting RRM2, NF-κB, cyclin D1 and pRb." (PMID 38473336, 2024). "In this study, we hypothesize that through the inhibition of RRM2, cyclin D1 and the NF-κB pathway, DDX can significantly halt the growth of ER+ and ER− breast cancer cells along with their PLB-resistant counterparts." (PMID 38473336, 2024). "Hence, high levels of cyclin D1, CDK4, and CDK6 are often observed in most patients with breast cancer." (PMID 39328201, 2024). "Surprisingly, high CCND1 levels did not predict outcomes in breast cancer patients, irrespective of the PIK3CA status." (PMID 38273040, 2024). "Indeed, it has been shown that activated GR binds to and represses the enhancer regions of the ER-mediated cell cycle genes’ (e.g., CCND1, CDK2, and CDK6) in ER+ breast cancer cells." (PMID 39519365, 2024). "CCND1-driven and IGF2-driven breast cancer have been widely reported." (PMID 39872660, 2024). "NDRG4 has been shown to act via signaling pathways such as cyclin-D1, p27, XIAP, and survivin to increase tumor growth and inhibit apoptosis in other types of cancer, but no information on NDRG4 signaling pathways has been reported in breast cancer." (PMID 38611020, 2024). "Apart from melanoma, curcumin effectively modulates the WNT/β-catenin pathway in breast cancer, as it inhibited proliferation and induced the apoptosis of breast cancer cells through the inhibition of DVL, β-catenin and cyclin D1, as well as through the downregulation of phospho-GSK3β and β-catenin." (PMID 39684513, 2024). "To determine whether palbociclib resistance leads to transcriptional changes, we assessed the mRNA expression of CCND1 and RRM2 in ER+ and ER− parental and PLB-resistant breast cancers." (PMID 38473336, 2024). "As MDA-MB-468 breast cancer cells already have higher levels of CCND1 and RRM2 expression, we did not observe additional increased expression in these genes with PLB resistance." (PMID 38473336, 2024). "“CYCLIN_D1.KE.V1.DN” gene signature includes genes downregulated in MCF-7 breast cancer cells heterogeneously over-expressing a mutant form of Cyclin D1 (K112E) lacking the ability to activate cyclin-dependent kinase 4 (CDK4)." (PMID 37700842, 2023). "The associations between cyclin D1 and good prognosis have not been uncommonly described in NSCLC, breast cancer, and bladder cancer." (PMID 36675501, 2023).
breast cancer (continued). "The fusion of macrophages and breast cancer cells strengthened the activity TCF/LEF transcription factor and promoted the expression of downstream target genes (including cyclin D1 and c-MYC), leading to the promotion of tumor progression, metastasis, and EMT process." (PMID 36721232, 2023). "KLF4 also functions as an oncogene to promote the proliferation of bladder cancer and breast cancer cells in the presence of RASV12-Cyclin-D1 signaling or the absence of P21." (PMID 37723138, 2023). "Cyclin D1 and CDK4 contribute to breast tumorigenesis through their interaction with the cell cycle and promote proliferation in endocrine-resistant breast cancer cells and, together with Rb, potentially influence breast cancer pathogenesis and progression." (PMID 37369022, 2023). "Panobinostat accelerated the expression of APCL and blocked Wnt/β-catenin pathway via promotion of β-catenin degradation in breast cancer, resulting in inactivation of β-catenin targets, including c-Myc, CD44, Cyclin D1 and c-Jun, which contributed to inhibition of tumor growth and metastasis." (PMID 36969235, 2023). "Mice lacking CCND1 or CDK4 were resistant to mammary tumor development driven by the HER2 oncogene, suggesting CCND1 as potential therapeutic target for HER2+ BC as well." (PMID 37438342, 2023). "CRKL induces cyclin D1 and phosphorylated extracellular signal-regulated kinase expression, overexpression of CRKL correlates with progression and malignant proliferation of human breast cancers." (PMID 36927310, 2023). "In breast cancer, the combination of CDK4/6i with endocrine therapy became standard procedure and is certainly essential to restrict adaptive events, via reduction of Cyclin D1 levels and Cyclin E1 activity." (PMID 37964967, 2023). "In breast carcinoma cells, viability and clonogenicity were negatively affected upon PSMD2 repression, cells were arrested in G0/G1 phase, and the level of the proteins involved in the progression of the cell cycle (CDK6 and CCND1) was significantly decreased." (PMID 37529110, 2023). "Additionally, this enhances caspase-3 activity and activates JNK signaling, leading to cyclin D1 downregulation and cell cycle arrest in G1-phase in MDA-MB-231 breast cancer cells." (PMID 35682855, 2022). "Finally, Cyclin D1 (CCND1) is a direct target of Notch signaling and contributes to breast cancer cell cycle progression and proliferation." (PMID 36476410, 2022). "Combination therapies might therefore elevate the response rates in FGFR2amp tumours, as proposed for FGFRi–CDK4/6i combination therapy in patients with breast cancer with FGFR2 and CCND1 amplifications." (PMID 35948633, 2022). "CCND1 amplification can predict sensitivity to CDK4/6 inhibitors such as abemaciclib, palbociclib, and ribociclib, although these agents have reported only limited efficacy as monotherapy in tumor types other than breast cancer." (PMID 35884537, 2022). "Our results suggested that miR-885-3p could suppress the proliferation of breast cancer cells, partially by suppressing the expression levels of CDK2/CCNE1 and CDK4/6/CCND1 and arresting the cell cycle in the G0/G1 phase." (PMID 35383130, 2022). "T. gondii infection decreased CCND1 expression and increased BRCA2 expression, which suggests that T. gondii infection could suppress breast cancer growth." (PMID 36341349, 2022). "The expression of key markers associated with proliferation (MKI67, PCNA, CCNB1, MYBL2, BUB1, CCND1), apoptosis (BCL2, CASP7, CASP8, CASP9, CASP3, BAX, APAF1), differentiation (CDH1, CD24, EPCAM, ESR1, NGFR, RUNX1), and breast cancer stemness (CD44, ITGA6, DNER, ALDH1A3, ABCG2, PROCR) was assessed." (PMID 35183258, 2022). "Similarly, the chemo-preventive effect of auraptene in human breast cancer cells (MCF-7 and MDA-MB-231) was reported due to the inhibition of cyclin D1 expression and cell cycle progression." (PMID 35267408, 2022).